ZNF497 (zinc finger protein 497)
Description:
May be involved in transcriptional regulation.
Synonyms: FLJ44773
Tractability: No criterion of Open Targets' tractability assessment is met for any kind of drug.
Gene: Protein-coding gene on chromosome 19 (58,354,357 to 58,362,848, reverse strand). Ensembl gene ENSG00000174586.
Subcellular location: Nucleus
Subcellular location (Human Protein Atlas): Nucleoplasm; Cell Junctions
Gene Ontology:
Molecular function: protein binding; DNA-binding transcription factor activity; RNA polymerase II cis-regulatory region sequence-specific DNA binding; sequence-specific DNA binding
Biological process: regulation of transcription by RNA polymerase II; negative regulation of DNA-templated transcription
Cellular component: nucleus
Genetic constraint (gnomAD): Loss-of-function variants: 0 observed, 0.43 expected, observed/expected ratio (o/e) 0, 90% interval 0 to 1.85. That is too few expected variants to judge how well the gene tolerates losing a copy. Missense variants: 930 observed, 612.47 expected, observed/expected ratio (o/e) 1.52, 90% interval 1.44 to 1.6. Synonymous variants: 422 observed, 277.82 expected, observed/expected ratio (o/e) 1.52, 90% interval 1.4 to 1.65.
Homologues: Orthologues: chimpanzee ZNF497 (99% identical), macaque ZNF497 (93% identical), zebrafish si:dkey-89b17.4 (30% identical), zebrafish znf646 (30% identical), Drosophila melanogaster zf30C (26% identical), zebrafish znf576.1 (20% identical), Drosophila melanogaster CG6791 (20% identical), Drosophila melanogaster hang (20% identical), Drosophila melanogaster CG1602 (19% identical), Drosophila melanogaster az2 (19% identical), Drosophila melanogaster CG3032 (18% identical), Drosophila melanogaster CG11695 (17% identical), and 15 more. Paralogues in human: ZNF84 (44% identical), ZNF160 (43% identical), ZNF91 (43% identical), ZNF184 (43% identical), ZNF594 (41% identical), ZNF420 (41% identical), ZNF107 (40% identical), ZNF347 (40% identical), ZNF99 (39% identical), ZNF208 (39% identical), ZNF473 (38% identical), ZNF665 (38% identical), and 24 more.